CDIPTOSP (CDIP transferase opposite strand, pseudogene)
Synonyms: lnc-CTHCC; formerly CDIPT-AS1
Gene: Transcribed unitary pseudogene on chromosome 16 (29,864,308 to 29,865,442, forward strand). Ensembl gene ENSG00000214725.
Diseases named in the same sentence as CDIPTOSP in open-access papers:
CDIPTOSP is named in the same sentence as 1 disease in open-access papers, as found by Europe PMC text mining. Sharing a sentence is not in itself a finding about the gene and the disease. The quoted sentences say what the papers report.
schizophrenia (1 paper, 2023). A major psychotic disorder characterized by abnormalities in the perception or expression of reality. "Furthermore, SEZ6L2, CDIPTOSP, ASPHD1, and RANBP1 are potential candidate genes for schizophrenia." (PMID 37486921, 2023).